OR52N2 (olfactory receptor family 52 subfamily N member 2)
Description:
Odorant receptor.
Synonyms: OR11-57
Tractability: Antibody: UniProt places it where antibodies can reach, with medium confidence; UniProt predicts a signal peptide or a membrane-spanning region; its Gene Ontology location is reachable by antibodies, with medium confidence.
Gene: Protein-coding gene on chromosome 11 (5,808,911 to 5,821,492, forward strand). Ensembl gene ENSG00000180988.
Subcellular location: Cell membrane
Pathways (Reactome):
Sensory Perception: Expression and translocation of olfactory receptors
Gene Ontology:
Molecular function: olfactory receptor activity; G protein-coupled receptor activity
Biological process: detection of chemical stimulus involved in sensory perception of smell; G protein-coupled receptor signaling pathway; nervous system process
Cellular component: plasma membrane; membrane
Homologues: Orthologues: chimpanzee OR52N2 (98% identical), mouse Or52n2 (88% identical), dog OR52N2 (88% identical), mouse Or52n2c (88% identical), rabbit OR52N2 (88% identical), rat Or52n2 (88% identical), rat Or52n2e (88% identical), macaque OR52N2 (87% identical), dog OR52N2G (83% identical), rat Or52n2b (81% identical), mouse Or52n2b (80% identical), tropical clawed frog or52ak1b (46% identical), and 3 more. Paralogues in human: OR52N1 (75% identical), OR52N4 (72% identical), OR52N5 (71% identical), OR52D1 (50% identical), OR52E4 (50% identical), OR52B2 (49% identical), OR52E2 (49% identical), OR52A5 (49% identical), OR52J3 (48% identical), OR52E8 (48% identical), OR52E5 (47% identical), OR52H1 (47% identical), and 39 more.